RN7SKP230 (RN7SK pseudogene 230)
Gene: Miscellaneous RNA gene on chromosome 5 (109,699,500 to 109,699,834, reverse strand). Ensembl gene ENSG00000202512.
Homologues: Paralogues in human: RN7SKP133 (71% identical), 7SK (71% identical), RN7SKP71 (71% identical), RN7SKP146 (70% identical), RN7SKP79 (70% identical), RN7SKP204 (70% identical), RN7SKP176 (70% identical), RN7SKP90 (70% identical), RN7SKP225 (69% identical), RN7SKP47 (69% identical), RN7SKP249 (69% identical), RN7SKP294 (69% identical), and 283 more.